MUC1 (mucin 1, cell surface associated)
Diseases named in the same sentence as MUC1 in open-access papers (continued):
Sharing a sentence is not in itself a finding about the gene and the disease.
cancer (continued). "The present study highlights the importance of targeting MUC1/Y for cancer treatment and unravels the suitability of a DNA aptamer to act as a new therapeutic tool." (PMID 34452200, 2021). "MUC1 currently ranks second among 75 candidate antigens for cancer vaccines and over the years, has been used as the basis for the development of different types of vaccines." (PMID 34207342, 2021). "Considerable efforts have been devoted to harnessing antibodies toward aberrantly glycosylated MUC1 as cancer immunotherapy, through vaccination with glyco-MUC1 peptides or passive immunization." (PMID 34640530, 2021). "Mucin 1 (MUC1) is a transmembrane glycoprotein that is aberrantly unregulated in numerous types of cancers, and serves as a key oncogene in the tumorigenesis of various human adenocarcinomas 31,32." (PMID 34729096, 2021). "MUC1 can lead to the emergence of drug resistance during cancer therapy as it is commonly overexpressed in various epithelial cancers." (PMID 34207342, 2021). "In the emerging field of targeted delivery, different antibodies or inducers against MUC1 have proven helpful for tracking cancer cells." (PMID 34207342, 2021). "Functionalized SDHs with doxorubicin and MUC1 showed high affinity toward the targeted cancer cells and entered inside the cell via receptor-mediated endocytosis." (PMID 34307293, 2021). "The presence of MUC16 neo‐antigen‐specific T cell clones and anti‐MUC1 antibodies in cancer suggests that MUCINs can serve as potential targets for developing cancer therapeutics." (PMID 34327857, 2021). "MUC1 mucin is a transmembrane glycoprotein aberrantly overexpressed and underglycosylated in most epithelium origin cancers." (PMID 34206951, 2021). "Given the cancer specificity of these 5E5-based antibodies, combined with the fact that many different tumors show expression of cancerous MUC1 epitopes, CIM301-1 but especially CIM301-8 are interesting candidates for cancer immunotherapy." (PMID 34070311, 2021). "The aberrant glycosylation of MUC1 in both cancers and premalignant lesions makes it a valuable target, which was recognised in a National Cancer Institute (NCI) report from 2009 ranking MUC1 as one of the most promising peptides for cancer immunotherapy." (PMID 34066318, 2021). "In order to assess the binding of the S11 aptamers to the full-length biomarker and investigate which cancer cell lines express MUC1/Y, flow cytometry was performed." (PMID 34452200, 2021). "MUC1 blocks this nuclear translocation of the c-Abl protein and thereby inhibits the apoptotic response to genotoxic anti-cancer drugs." (PMID 34681277, 2021). "For example, MUC1 is often overexpressed in cancer and plays a key role in cancer progression, increasing the bulkiness of the glycocalyx to help cells survive anoikis." (PMID 34625644, 2021). "The transmembrane glycoprotein mucin 1 (MUC1) is a mucin family member that has different functions in normal and cancer cells." (PMID 34207342, 2021). "Currently, Tn-MUC-1 CAR-T cells and cancer vaccines targeting Tn-MUC1 are investigated preclinically." (PMID 34638920, 2021). "MUC1 promotes the migration and invasion of a variety of cancers; the regulatory mechanisms governing this phenomenon are highly redundant and complex." (PMID 34207342, 2021). "Transmembrane MUC1 is also engaged in transducing cellular signaling cascades through interacting with receptors for growth and differentiation in cancer cells." (PMID 33836774, 2021). "Several studies have generated and modified CAR T cells targeting MUC1, and have investigated their functional efficacies in several cancer models." (PMID 33737613, 2021). "CDNs have also been evaluated with a number of other cancer antigens and cancer vaccines, including MUC1 glycopeptide, a B16 melanoma peptide, and a mouse model of glioma and EG7-Ova tumour." (PMID 34452042, 2021). "This review has highlighted the structural features of MUC1 and its primary functions in cancer progression." (PMID 34207342, 2021).
cancer (continued). "This therapeutic vaccine provides immunity to kill the cancer cells expressing a glycoprotein antigen of Mucin 1 (MUC-1)." (PMID 33918072, 2021). "For instance, MUC1 that is overexpressed in many cancer types has been reported to interact with Siglec-1 and Siglec-4, mediating adhesion between Siglec-4 expressing Schwann cells and MUC1 expressing pancreatic cells." (PMID 34966391, 2021). "In this work, we demonstrate, for the first time, the development of a DNA aptamer against a MUC1/Y alternative splice variant aiming to obtain novel biopharmaceutics with improved specificity for MUC1/Y positive cancers." (PMID 34452200, 2021). "Here, we report that MUC1 regulates proliferation and suppressive phenotype of MDSCs in both healthy and cancer conditions." (PMID 34070449, 2021). "In summary, the levels of TNF-α and IFN-γ produced by anti-MUC1-CAR4 T cells were related to MUC1 expression on the cancer cell membrane." (PMID 33737613, 2021). "The data from the single-cell RNA-sequencing, along with the well-established tumoral antigens like MUC1, can help us design the desired mRNA in heterogeneous and ever-progressing cancers." (PMID 33692796, 2021). "This vaccine produces a CTL that recognizes both glycosylated and non-glycosylated peptides, thereby effectively circumventing the failure of CTLs and IgG antibodies in targeting cancer expressing MUC1 due to conformational dissimilarities." (PMID 34207342, 2021). "We were particularly interested in studying those genes that are associated with cancer progression, TME signals, and poor prognosis such as LY6E, NAPSA, MUC1, ELF3, and FOS." (PMID 33144684, 2021). "MUC1 promotes proliferation and invasion of cancer cells through the activation of the PI3K/Akt/mTOR and ERK1/ERK2 pathways." (PMID 34770912, 2021). "The interaction between MUC1 and IGF-1R causes IGF-1R to become a powerful angiogenic factor in cancer cells." (PMID 33836774, 2021). "It has been known that mucin 1 (MUC1) is a cell surface mucin that highly expressed in various cancer tissues." (PMID 34729096, 2021). "The association of overexpressed or aberrantly glycosylated Mucin 1 (MUC1) with poor prognosis and malignant behaviors in many types of cancers has been reported." (PMID 34641504, 2021). "VHHbased anti-MUC1 redirectedT cells were activated upon recognition of MUC1 expressing cancer cells and showedsignificant cytokine production and cytotoxic activity." (PMID 32347044, 2021). "This review introduces the biological structure and different roles of MUC1 in normal and cancer cells and the regulatory mechanisms governing these roles." (PMID 34207342, 2021). "Altered MUC1 glycosylation also promotes chronic inflammatory conditions that lead to malignant transformation and cancer progression." (PMID 34207342, 2021). "A remarkable depolarized expression of MUC1 glycoprotein throughout the entire cell surface has been reported in a large number of carcinomas of the breast, ovary, rectum, pancreas, colon, and prostate." (PMID 33836774, 2021). "MUC1′s physiological properties and widespread expression in many different types of human epithelial carcinomas has led it to become the primary focus of many cancer vaccine development projects." (PMID 34065557, 2021). "In many cancers of epithelial origin, overexpression of MUC1 in cancer cells participates in regulating cancer progression, including the EMT33." (PMID 33060563, 2020). "In cancer cells, MUC1 has been shown to drive self-renewal capacity and promote stemness of cancer cells." (PMID 32793510, 2020). "For example, the mucin MUC1 is aberrantly expressed in the majority of cancers diagnosed each year in the United States." (PMID 33024038, 2020). "A Phase I clinical trial employing AR20.5 as a monotherapy in 17 patients with MUC1-expressing cancers found that the antibody was generally well-tolerated and induced MUC1-specific immune responses but did not produce a significant therapeutic effect." (PMID 32429033, 2020).
cancer (continued). "MUC1 promotes cancer cell invasion and epithelial‐to‐mesenchymal transition (EMT) through its interaction with beta‐catenin, both of which are reduced upon treatment with SAM + 5AzadC." (PMID 32720467, 2020). "MUC1 is a highly expressed gene in a variety of cancers, including OvCa, and is known to participate in tumorigenicity, initiate the EMT process, and coordinate cancer metastasis." (PMID 32587475, 2020). "It has been reported that MUC1 undergoes autocleavage into MUC1-N and MUC1-C, and MUC1-C accumulates in cancer cells and binds to TFs or TCAs to improve their function by increasing their nuclear translocation." (PMID 33060563, 2020). "MUC1 can disrupt and upregulate key pathways to facilitate the proliferation and metabolism of cancer cells." (PMID 33379259, 2020). "MUC1 is overexpressed in several cancer types, including adenocarcinoma, making it a suitable target for CAR-T therapy." (PMID 32751977, 2020). "MUC1 is a glycoprotein that is markedly hypoglycosylated in cancer compared to normal tissues, leading to the exposure of immunogenic epitopes." (PMID 33679709, 2020). "We also present our perspectives on how the mechanisms of action of different anti-MUC1 antibodies can target specific hallmarks of cancer and therefore be utilized as a combination therapy for better clinical outcomes." (PMID 33167508, 2020). "In normal cells, MUC1 is heavily glycosylated, so its antigenic epitopes are shielded from the immune system; in contrast, MUC1 is under-glycosylated and overexpressed (~100-fold) on the surface of cancer cells." (PMID 32075083, 2020). "Accordingly, a number of clinical and preclinical studies have delved into MUC1-mediated cancer immunotherapy and vaccination (reviewed elsewhere)." (PMID 32377198, 2020). "MUC1 not only serves as a cancer biomarker but also functions to regulate several biological events of cancer including proliferation, invasion, immune‐therapy and drug resistance." (PMID 32596961, 2020). "Another example of a shared antigen that is differentially displayed to T cells by cancer cells compared to normal cells is MUC1." (PMID 32942747, 2020). "By confocal microscopy of immunostaining assay, Avery Posey found the Tn (GalNAcα1-O-Ser/Thr) glycoform of MUC1 (Tn-MUC1) expressed intracellularly in normal tissue such as human kidney, but at the cell membrane in several cancers." (PMID 32194541, 2020). "The high antitumoral efficacy of 16A‐MMAE suggests that aberrant glycosylated MUC1 neoantigen is a potential target for the development of ADCs for treating various cancers." (PMID 33084221, 2020). "The unmasking of the VNTR region gives different antigenic profiles between cancer-specific and physiological MUC1." (PMID 33379259, 2020). "Bromelain showed be capable of counteracting MUC-1 onco-glycoprotein overexpression that should impart enhanced proliferation and antiapoptotic feature to cancer cells along with conferring invasiveness and chemoresistance to various human tumors." (PMID 34466585, 2020). "MUC1 has been widely studied for many years because of its oncogenic features in various cancers including PC." (PMID 32745356, 2020). "MUC1-C is a transmembrane subunit of the MUC1 glycoprotein, which can translocate into the nucleus and trigger expression of other cancer-related oncogenes." (PMID 33208183, 2020). "MUC1 is also considered a novel metabolic master regulator of glucose and lipid metabolism to maintain cancer cell survival under nutrient-deprived conditions." (PMID 33060563, 2020). "The transmembrane glycoprotein MUC1 is the most likeable target for antibodies, owing to its specific overexpression and aberrant glycosylation in many types of cancers." (PMID 33167508, 2020). "The expressionlevels of MUC1 in various human cancers have illustrated its function in cancer pathogenesis." (PMID 34803270, 2020).
cancer (continued). "TG4010, a therapeutic cancer vaccine, expressing MUC1 as well as interleukin 2, and is combine with PD-L1 immune inhibitor nivolumab, has been approved by the FDA for the first-line treatment of patients with NSCLC." (PMID 33208183, 2020). "On the one hand, activation of MGL on DC’s by synthetic glycopeptides carrying Tn structures (e.g., from CD45, CD43 or MUC1), showed an immunosuppressive response in cancer." (PMID 32752259, 2020). "In the present study, to prepare a human cancer vaccine targeting MUC1, CpG 2006 was used as an adjuvant to improve the immunogenicity of MUC1-MBP." (PMID 32823603, 2020). "The HeLa cancer cell membranes were functionalized with a nucleic acid that included the MUC-1 aptamer sequence conjugated to a nucleic strand complementary to the uncaged, fragmented, hairpin units associated with the liposomes." (PMID 32874503, 2020). "Previous studies have demonstrated that MUC1 is overexpressed in several cancers including breast cancer and pancreatic cancer." (PMID 32596961, 2020). "Both MUC1-Bi-1 and its humanized version specifically detected tMUC1 on several cancer cell lines (SKOV3, HT29, and LS174) and potentially introduced them to NK cells." (PMID 33167508, 2020). "The increase in MUC1 expression is consistent with that observed in cancer cell lines and the decrease of MUC5AC expression is in agreement with previous results in lung epithelial cells." (PMID 32033337, 2020). "High levels of circulating autoantibodies against both the cancer‐specific MUC1 isoform and the non‐glycosylated signal peptide domain of MUC1 (up to 200 μg/ml) have been reported in human cancers." (PMID 33084221, 2020). "After vaccination, all the evaluable patients with MUC1-positive cancer acquired antigen-specific immunity compared to only one patient with MUC1-negative cancer." (PMID 33679709, 2020). "With MUC1 being aberrantly expressed in a variety of cancers, such as Pancreatic Ductal Adenocarcinoma, its translation to other cancer is being explored." (PMID 32645977, 2020). "Mucin1 (MUC1) is aberrantly glycosylated and overexpressed in various cancers, and it plays a crucial role in cancerogenesis." (PMID 32380650, 2020). "Our data indicate that at least one of the mechanisms whereby MUC1-ST can affect progression of cancers is by the direct induction of monocyte differentiation into macrophages with a TAM-like phenotype without the need for any additional factor." (PMID 33149188, 2020). "In pancreatic intraepithelial neoplasia, AGR2 acts as a SMAD4-suppressible gene that regulates MUC1 levels and stimulates the initiation and progression of cancer." (PMID 32322663, 2020). "To validate these results, we performed flow cytometry analysis of known surface molecules implicated in cancer progression including frizzled 7 (FZD7), CD44, MUC-1, and integrins α2, β4, αvβ3, β3, and α4." (PMID 32352029, 2020). "In contrast, miRNA-145 was observed to be low in BM and directly targets mucin 1 (MUC1), a gene associated with the metastatic ability of cancer cells." (PMID 31900168, 2020). "SM-88 is believed to directly interfere with cancer cells’ ability to synthesize critical proteins, including the protective transmembrane protein Mucin 1 (MUC1)." (PMID 30929156, 2020). "While MUC1 is expressed by normal epithelial cells and cancer cells, the protein is aberrantly under-glycosylated in cancer cells." (PMID 32429033, 2020). "This exposes the VNTR region and leads to an aberrant overexpression and redistribution of MUC1 in cancer cells." (PMID 33379259, 2020). "We have also provided perspectives on how different anti-MUC1 antibodies target different hallmarks of cancer and thus can be utilized as a combination therapy to have better clinical outcomes." (PMID 33167508, 2020). "First, we selected MUC1 as our research target and verified its differential expression in cancer tissues and adjacent non‐neoplastic tissues (ANNT)." (PMID 31800160, 2020).
cancer (continued). "In contrast, combinations of several markers have proved to be of superior diagnostic value, such as the combination of EMMPRIN/EpCAM/MUC1/EGFR, which reliably separated cancer patients from healthy controls with a high AUC value of 0.85." (PMID 32731639, 2020). "The authors demonstrated that the developed aptasensor had high affinity and specificity for MUC1+ NSCLC cells (A549), discriminating them from MUC1− normal lung cells (MRC-5) or cells from other cancers (human prostate and liver tumors)." (PMID 32842557, 2020). "The aberrant glycosylation of MUC1 is found many in carcinomas as is the upregulation of ST3Gal-149." (PMID 33149188, 2020). "Mucin 1 (MUC1) is a heterodimeric protein that is aberrantly overexpressed in diverse human carcinomas and contributes to hallmarks of the cancer cell, including EMT, stemness, anti-cancer drug resistance, epigenetic reprogramming, and immune evasion." (PMID 31953400, 2020). "MUC1 expression has been shown to be up to 10 times higher in many human carcinomas than in normal tissues, which provides resistance to chemotherapy." (PMID 33167508, 2020). "In the same manner as MUC1, MUC4 overexpression in cancer promotes IPF-linked processes including myofibroblast transition, proliferation, migration and metastasis." (PMID 31514468, 2019). "This study aimed to evaluate the anti-cancer effect of a combination therapy of miRNA-29b and genistein loaded in mucin-1 (MUC 1)-aptamer functionalized hybrid nanoparticles in non-small cell lung cancer (NSCLC) A549 cell line." (PMID 31340494, 2019). "One such target is localized on the apical region of normal epithelial cells, but gets aberrantly overexpressed in various cancers in human epithelial mucin 1 (MUC1), which received considerable interest as a cancer antigen target." (PMID 31470531, 2019). "Taken together, these data indicate that the combination of targeting either EGFR or MUC1 and paclitaxel blocks paclitaxel-resistant CSCs, and thereby prevents recurrence of MUC1-positive cancer." (PMID 31772161, 2019). "In contrast, phosphorylation has been extensively studied in MUC1 where phosphorylation correlates with altered cancer cell properties in pancreatic and ovarian cancer cell lines." (PMID 31387973, 2019). "MUC1 also contributes to the malignant phenotype of cancer cells by binding to β-catenin, blocking phosphorylation and degradation." (PMID 31430935, 2019). "We had a much smaller number of IPMN patients this time so we combined them with the cancer patients, some of whom were positive for anti-MUC1 IgG." (PMID 31275327, 2019). "A well-known cancer biomarker, MUC1, is expressed at nine-fold higher in exosomes than total membrane proteins." (PMID 30646616, 2019). "In line with this, anti-MUC1 antibodies have already been shown to inhibit EGF receptor signaling in cancer cells." (PMID 30642093, 2019). "In this study, the MPLA was used as a TLR4 ligand, and mucin 1 (MUC1) was used as a cancer-involved antigen." (PMID 30691225, 2019). "Since MUC1 is a widely used biomarker in cancer clinics, we tried to measure the exosomal MUC1 by commercially available tests that are currently used in clinics." (PMID 30646616, 2019). "Recently, a synthetic cancer vaccine candidate consisting of a MUC1 glycopeptide and B-cell epitope was used to break the self-tolerance of the immune system." (PMID 31696111, 2019). "In spite of potential challenges with pharmacokinetic properties, glycopeptide structures linked to immunostimulants have in recent years shown to be highly efficient as potential MUC1 anti-cancer vaccines and a number of candidates are in clinical trials." (PMID 30871155, 2019). "MUC1 is a glycoprotein that has been reported to play a key role as an oncogene inducing the tumorigenicity of many human cancers." (PMID 31071912, 2019). "The differences of MUC1 between normal and cancer cells make it a promising target for cancer therapy." (PMID 30699986, 2019).